CRP (C-reactive protein)
Diseases named in the same sentence as CRP in open-access papers (continued):
Sharing a sentence is not in itself a finding about the gene and the disease.
tumor (continued). "In other words, preoperative CRP/MCV could predict aggressive tumor biology, which is conducive to risk stratification and guiding clinical work." (PMID 34221966, 2021). "CRP is associated with prognosis independently of grading and tumour stage and may be of additional use for treatment decisions." (PMID 34887479, 2021). "The inflammatory response related to an AL has been proposed to stimulate tumour proliferation and evolution to distant metastasis, with elevated levels of inflammatory markers such as C-reactive protein (CRP) associated with higher recurrence rates and impaired disease-free survival." (PMID 34070593, 2021). "Similarly, among 115 patients with CRPC on docetaxel, CRP ≥ 8 mg/L was associated with higher risk of tumor progression and shorter overall survival." (PMID 34512646, 2021). "The relationship between chosen risk factors (serum CXCL8 and its specific receptor —CXCR2 as well as classical tumor markers and CRP) and GC risk was examined using univariate analysis to assess the risk factors that subsequently were employed in the multivariate model." (PMID 34680333, 2021). "An elevated CRP level reflects the inflammatory response caused by tumor necrosis." (PMID 34765598, 2021). "Additionally, tumor characteristics associated with an aggressive biology, such as G3 grading (p = 0.048) and size ≥3 cm (p = 0.090), were more common in the high-CRP group." (PMID 32423000, 2020). "This hypothesis is supported by previous findings demonstrating an association between CRP levels and tumor size." (PMID 32182693, 2020). "Moreover, the pathway enhances the formation of CRP-mediated tumor microenvironment by activating tumor-associated macrophages and tumor angiogenesis." (PMID 33013829, 2020). "High CRP could result from immune response of the body to tumor antigens or tissue inflammation caused by tumor growth." (PMID 32181373, 2020). "CRP in its monomeric, modified isoform (mCRP) modulates inflammatory responses by inserting into activated cell membranes and stimulating platelet and leukocyte responses associated with acute phase responses to tumor growth." (PMID 33324413, 2020). "C-reactive protein is a marker of inflammation, and an elevated serum level might be caused by tumour necrosis or local tissue damage." (PMID 33028394, 2020). "We thus investigated whether the CRP level at the time of diagnosis was significantly associated with clinical characteristics, tumor characteristics, comorbidity scores, or cytokine serum levels." (PMID 32707675, 2020). "Before matching, univariate analysis showed that age (p < 0.001), TNM stage (p = 0.001), history of alcohol consumption (p = 0.024), tumor grade (p = 0.039), and preoperative serum CRP levels (p = 0.008) were significant risk factors for postoperative survival." (PMID 31533862, 2019). "In that study, levels of sPD-1 and sPD-L1 were closely correlated and elevated in association with an elevated c-reactive protein, suggestive of systemic inflammation, and tumor infiltration with T cells, which was consistent with an active anti-tumor immune response that was being blunted." (PMID 31523394, 2019). "The reason why the PNI is a more powerful prognostic factor than the CRP/Alb ratio and mGPS may be that circulating lymphocyte counts are associated more positively with the tumor response to CRT than is the CRP." (PMID 30974894, 2019). "In addition, we found that CRP was positively associated with mortality in patients with tumor resection, which support the positive association between CRP and mortality in patients with resectable NSCLC10,12,14." (PMID 31148582, 2019). "TSH and fT4 were associated with prognostic factors of HCC (i.e., tumor size, CRP level)." (PMID 28771610, 2017). "In addition, a series of work by McMillan and other groups outlined the indisputable association between an increased CRP level and poor survival in various tumor types." (PMID 28717855, 2017).
tumor (continued). "Additionally, elevated serum CRP levels are associated with increased IL-6 production by tumor cells or by surrounding tissues." (PMID 29262550, 2017). "Elevated CRP levels are associated with tumor stage and locoregional invasiveness." (PMID 28209200, 2017). "High CRP and high leukocytes, which may reflect inflammation caused by the tumor as well as individual comorbidities, were also poor prognostic factors for patients in this cohort." (PMID 28686697, 2017). "Second, this could be explained by reverse causality, or that tumor progression increases the CRP level." (PMID 27733196, 2016). "However, elevated preoperative C-reactive protein associated with higher tumour size (P < 0.05), vascular invasion (P < 0.05), and poor differentiation (P < 0.05)." (PMID 27689078, 2016). "Recently, one study found CRP was associated with tumor size in NSCLC." (PMID 27303917, 2016). "CRP >5 mg/L was associated with advanced tumor stage, lower albumin level, and lower PFSR." (PMID 26799163, 2016). "First, this phenomenon could be explained by causality, or that an elevated CRP level promotes tumor progression." (PMID 27733196, 2016). "As a component of the inflammatory response of the immune system, CRP exerts important role in the tumor-host interaction, and elevated CRP is associated with impaired T lymphocytic response within the tumor." (PMID 27104127, 2016). "However, the positive correlation of blood and ascites CRP levels and the association of higher levels of serum CRP with worse prognosis is in line with our previously published results of a worse overall survival of HGSC patients with miliary tumor spread." (PMID 27665539, 2016). "The majority of studies assumed that elevated serum CRP levels in patients with malignancy constituted a bodily response, secondary to tumor necrosis, local tissue damage and inflammation caused by cytokines released from leukocytes infiltrating the tumor microenvironment, in particular IL-6." (PMID 26848624, 2016). "The causal role of CRP in tumor progression merits further investigation in preclinical studies." (PMID 27733196, 2016). "The association of higher CYPFRA 21-1 and CRP with distant metastasis could be attributed to the advanced tumor stage or the existence of circulating tumor cells." (PMID 26292957, 2015). "Taken together, the cited reports postulated a wide range of hypothesises regarding the molecular basis of the association between elevated CRP serum levels, inflammation and tumor progression." (PMID 26248232, 2015). "A higher level of the CRP/Alb ratio was associated with larger tumor size (P < 0.001), poorer differentiation (P = 0.019), deeper tumor invasion (P = 0.003), more lymph node metastasis (P = 0.015), more distant metastasis (P < 0.001) and later TNM stage (P < 0.001)." (PMID 25934640, 2015). "In addition, FIGO surgical staging (recommended as a formal step in initial treatment) showed significant associations with CA125, CA15-3, CRP, and D-D Concentrations in our study, these indicate that they are closely related with tumour pathophysiology." (PMID 26107255, 2015). "However, it was found that a higher CRP/Alb ratio level (>0.095) was associated with more lymph node metastasis (P = 0.015), deeper tumor invasion (P = 0.003), more distant metastasis (P < 0.001) and more advanced TNM stage (P < 0.001)." (PMID 25934640, 2015). "Elevated CRP levels (CRP ≥5.0 mg/L) were found to be associated with the skin invasion (P = 0.009), bone invasion (P < 0.001), tumor depth (≥10 vs. <10 mm, P < 0.001), pathological tumor status (P < 0.001), and pathologic nodal metastasis (P = 0.049)." (PMID 26292957, 2015). "First, tumor growth itself can cause inflammation of surrounding tissue and increase plasma CRP." (PMID 26717416, 2015).
tumor (continued). "An SCC-Ag level ≥2.0 ng/ml and a CRP level ≥5.0 mg/L at the time of recurrence were significantly associated with recurrent tumor status (P<0.001), recurrent nodal metastasis (χ2 trend test: P = 0.020), distant metastasis (P<0.001), and overall survival (P<0.001)." (PMID 25061977, 2014). "The association with elevated CRP levels and a dismal prognosis might reflect the prognostic value of tumor produced interleukin-6, an inducer of CRP production in the liver." (PMID 24885814, 2014). "Elevated CRP levels may be due to underlying malignancy or premalignancy or to tissue inflammation associated with tumor growth." (PMID 23642165, 2013). "Furthermore, elevated serum CRP levels are associated with higher tumor burden and advanced tumor stages, which will, to certain extent, be related to the dynamic changes of CRP." (PMID 24130817, 2013). "Moreover, elevated levels of SCC-Ag and CRP were associated with a high metabolic rate as well as the proliferative activity measured according to the SUVmax of the tumor and lymph nodes." (PMID 23383155, 2013). "A close association was observed between elevated hs-CRP levels (CRP>5.0 mg/l) and clinical lymph nodal status (P<0.001), distant metastasis (P=0.012), vascular and perineural invasion (P<0.001 and P<0.001), tumor differentiation (P=0.022) and clinical stage (P=0.001)." (PMID 24255664, 2013). "On the other hand, sustained inflammation may reflect a pro-angiogenic environment, as circulating concentrations of vascular endothelial growth factor are directly associated with CRP, allowing unrestrained tumour growth and dissemination." (PMID 22433965, 2012). "Furthermore, MDR1, MRP, and LRP expression wasn’t associated with tumor stage, response to first-line therapy, the erythrocyte sedimentation rate, or C reactive protein, beta 2 microglobulin, serum lactate dehydrogenase, and albumin levels." (PMID 24744642, 2012). "In sub-analyses stratified for age at diagnosis and prognostic tumour characteristics, elevated CRP levels across tertiles were associated with reduced overall survival irrespective of presence of distant metastases, and estrogen and progesterone receptor status." (PMID 21639875, 2011). "In addition, it has been suggested that increased CRP was associated with more frequent local tumor invasion, more advanced pathologic stage, a higher rate of recurrence, and reduced overall survival." (PMID 20465852, 2010). "Therefore, in EAC-solid tumor model, we evaluated the chemopreventive effects of DHA, its impact on that of CP, and the utility of c-reactive protein (CRP) as a diagnostic/prognostic predictor of this tumor growth and/or responsiveness to chemotherapy." (PMID 19341447, 2009). "It is entirely possible that underlying occult tumours in any subjects discussed in this review may be influencing CRP levels." (PMID 19732183, 2009). "Clearly, both these tumour and host mechanisms may be related and required for the greater malignant potential associated with an elevated C-reactive protein concentration." (PMID 16523196, 2006). "Clearly, both these mechanisms may be related and promote unrestrained tumour growth and the dissemination required for the greater malignant potential associated with an elevated C-reactive protein concentration." (PMID 16685271, 2006). "Clearly, both these inflammatory mechanisms may be related and promote unrestrained tumour growth and the dissemination required for the greater malignant potential associated with an elevated C-reactive protein concentration." (PMID 16721360, 2006). "When compared with tumour sections possessing lymphoid aggregates alone, tissues with a diffuse or patchy inflammatory cellular infiltrate were associated with elevated serum CRP and sTNF-R concentrations (P=0.01 and P=0.007, respectively, Mann–Whitney U-test)." (PMID 17088911, 2006).
tumor (continued). "Key predictors consistently linked to the risk of developing AL were as follows: tumor location in relation to the anal verge (e.g. distances <5 cm), intra-operative factors such as blood loss >100 mL, and postoperative laboratory results [elevated creatinine, C-reactive protein (CRP)]." (PMID 40844287, 2025). "Therefore, high levels of CRP reflect an immunosuppressive tumor microenvironment and hence may be associated with worse outcomes in several malignancies." (PMID 40740873, 2025). "The authors postulated that CRP could serve as a valuable prognostic factor for risk assessment and treatment decisions, attributing the link between CRP and disease progression to inflammation within the tumour microenvironment." (PMID 38332520, 2024). "Indeed, the presence of acalculous AC and lower levels of CRP may reflect the presence of other severe underlying comorbidities, such as hepatic impairment and neoplastic diseases." (PMID 38396453, 2024). "However, transient CRP elevation early after ICI administration may be caused by the activation of anti-tumour immunity by the ICI treatment." (PMID 39516365, 2023). "Previous studies have focused on whether pretreatment CRP/Alb ratio is a sensitive factor for predicting tumor prognosis and found consistent results: the elevated pretreatment CRP/Alb ratio was associated with a shorter OS in tumor patients." (PMID 37735699, 2023). "Furthermore, elevated CRP was associated with poorer tumor regression." (PMID 34070592, 2021). "Furthermore, analysis of 366 HCC tumor samples from TCGA demonstrated positive associations of tissue CRP level and genes related to myeloid cells, including CD68 and CD14, as well as chemokines and receptors for the chemotaxis of monocytes or neutrophils, such as CCL2, CCR2, and CXCL1." (PMID 35070979, 2021). "Also, higher CRP levels were significantly associated with a higher tumour grade (p < 0.001), higher T status (p < 0.001), positive lymph node status (p < 0.001) and distant metastases (p < 0.001),) reflecting more advanced and aggressive tumours." (PMID 34887479, 2021). "C-reactive protein is a biomarker of the inflammatory response that is produced by the liver; at increased levels, it may cause the body to create a microenvironment that is conducive to tumor cell proliferation and metastasis." (PMID 34257601, 2021). "First, tumor growth might cause tissue inflammation and CRP elevation." (PMID 33059654, 2020). "While the predominant utility of CRP as a biomarker has traditionally been as a non-invasive diagnostic, it may also be useful to measure CRP by immunohistochemical methods or in tumor explant lysates, especially in the evaluation of CRP under controlled conditions in in vivo xenograft experiments." (PMID 33324413, 2020). "CRP could also lead to excessive cell proliferation and subsequent DNA damage by promoting chronic inflammation which might increase the mutation burden in local tumors and make the tumor more sensitive to anti-PD-1 therapy." (PMID 31662753, 2019). "Therefore, increased CRP from baseline may cause inflammation by tumor development and growth or immune-related adverse event rather than an antitumor response from immunotherapy." (PMID 31443339, 2019). "Seven parameterclasses may constitute a reasonable initial framework for building the so-named“Cancer immunogram”, including the evaluation of tumor mutation load,lymphocyte count, intratumoral T cells, PD-L1 expression on tumor, serum levels ofc-reactive protein (CRP), LDH and IL-6." (PMID 29552325, 2018). "In an adjusted proportional hazards model including WHO performance status and levels of ALP, CEA and CRP, an elevated level of serum CA 19-9 was associated with a significant relative reduction in survival (adjusted HR = 4.35 (95% CI 2.89–8.28) in patients with tumours harbouring BRAF mutation." (PMID 29872151, 2018). "Furthermore, CRP was found to be significantly associated with larger tumor-size." (PMID 28970578, 2017).
tumor (continued). "However future prospective testing will need to incorporate a variety of immunologic predictive biomarkers such as serum lactate dehydrogenase and C reactive protein and tumor PDL-1 status, mutation load, T cell subsets and changes in and presence of tumor infiltrating lymphocytes." (PMID 29041991, 2017). "In this study, the reasons for the association with serum CRP levels and the efficacy of nivolumab remain unclear, but serum CRP and IL-6 levels have previously been shown to predict tumor response and survival to immunotherapy, such as high dose IL-2, IFN alpha, and ipilimumab." (PMID 29262550, 2017). "Hence, diagnostic measurement of serum CRP might be useful to indicate highly aggressive TETs and to make doctors consider tumor recurrences during oncological follow-up." (PMID 28514756, 2017). "In fact, whether serum CRP level is associated with tumor characteristics remains controversial." (PMID 25602444, 2015). "One reason may be that tumor growth can cause tissue inflammation and hence increased CRP levels." (PMID 26715527, 2015). "The clinical analyses using KM plots and Cox regression analysis showed that tumor stage and other variables related to clinical chemistry parameters—Glucose, Bilirubin, Creatinine, CRP, and triglycerides may be putatively associated with relapse status and survival." (PMID 24312117, 2013). "Furthermore, elevated CRP levels were associated with reduced overall survival separately in women above 57 years, with small and middle-sized tumours, positive lymph node status, moderately and poorly/undifferentiated tumours, and HER2 positive tumours." (PMID 21639875, 2011). "The correlation curves we constructed indicated a high degree of positive association between tumor size and both of CRP level and leukocytic count (r = 0.85 and 0.89; respectively), thus supporting our hypothesis that CRP may well serve as a prognostic and/or diagnostic factor in this tumor model." (PMID 19341447, 2009). "In the present study, CRP levels increased accordingly after the mice were grafted with human tumor cells, as their bodies had been invaded by foreign substances." (PMID 41530841, 2026). "Most values, including white blood cell count, neutrophil percentage, lymphocyte percentage, monocyte percentage, C-reactive protein level, and tumor markers, were comparable between the two groups." (PMID 41496777, 2026). "Key markers included C-reactive protein, albumin, neutrophil and lymphocyte counts, creatinine, bilirubin, international normalized ratio, tumor size and number, alpha-fetoprotein, platelet count, and CD4+/CD8+ T-cell levels." (PMID 41869666, 2026). "PCT, CRP, tumor T stage, SSAV Range, SSAV Max, and SSAV Min were demonstrated to be independent risk factors." (PMID 41939974, 2026). "CRP, a sensitive marker of systemic inflammation, is elevated under pro-inflammatory conditions and reflects the activity of a tumor-supportive microenvironment." (PMID 41566198, 2026). "Tumor cells release cytokines like IL‐6, CRP, and TNF‐α, as well as chemokines, angiogenic factors, and growth factors, inducing inflammatory responses that can promote or inhibit tumor growth." (PMID 40387308, 2025). "The high levels of CRP, an acute-phase protein, are indicative of a pro-inflammatory state driven by cytokine release (e.g., interleukin-6), which supports tumor growth, angiogenesis, and immune evasion." (PMID 39859125, 2025). "Although direct evidence of CRP regulating glycolysis in tumor cells remains limited, several lines of evidence suggest that CRP contributes to glycolytic programming through immune and metabolic pathways relevant to the TME." (PMID 41614767, 2025). "Known effects of endurance exercise that can reduce tumor growth include a reduction in C-reactive protein (CRP) levels and the release of inflammatory markers such as IL-6, sex hormones, insulin response, and vascularization." (PMID 40362215, 2025).